IL1B (interleukin 1 beta)
Diseases named in the same sentence as IL1B in open-access papers (continued):
Sharing a sentence is not in itself a finding about the gene and the disease.
Obesity (continued). "Moreover, the NLRP3 rs10754558 polymorphism, which leads to higher production of IL-1β and thus resembles a gain-of-function mutation, and the IL1B rs16944 polymorphism have been associated independently by various groups with T2DM and obesity." (PMID 37239938, 2023). "Additionally, a recent study showed that IL-1β produced by NLRP3-activated visceral AT might be responsible for obesity-related cognitive impairment." (PMID 36994095, 2023). "Obesity was associated with decreased serum levels of Eotaxin and KC, and elevated serum levels of G-CSF, TNF-α in offspring mice, while KD alone was associated with elevated serum levels of G-CSF, IL-1b, IL-6, RANTES, TNF-α and decreased serum levels of IL-1a, IL-9, IL-12 (p70)." (PMID 37686855, 2023). "The tissue inflammatory state during obesity may be caused by TLR-4/NF-κB pathway activation in macrophages via FFA action, which promotes the synthesis and secretion of proinflammatory cytokines, including IL-6, TNF-α, IL-1β, and IL-18." (PMID 37372966, 2023). "By combining both autochthonous GEMMs and syngeneic transplant models, the Jain group demonstrated that obesity (HFD and Lepob/ob induced) enhances PDAC-associated desmoplasia via increased PSC activation by tumor-associated neutrophils (TANs) recruited by adipose-derived IL1β." (PMID 37648285, 2023). "Moreover, it has also been reported that obesity-induced NLRC4 inflammasome in tumor-infiltrating myeloid cells promotes angiogenesis in diet-induced obese mice through IL-1β, and that such activation would finally lead to increased Vegfa expression in surrounding adipocytes." (PMID 37819510, 2023). "Transferring the data generated mainly in mice to humans would mean that inhibition of the NLRP3 inflammasome or IL-1β, as promising as it appears for treating obesity-associated morbidities, is not a suitable option for prevention of adiposity and its related metabolic diseases." (PMID 37239938, 2023). "While many immune cells including AMs, monocytes, T and B cells infiltrate AT in obesity, the highly significant decreases in IL-1β and IL-6 suggest that inhibition of the inflammasome in AT macrophages could play a pivotal role in the reduction of HFWD-induced cytokines." (PMID 34976743, 2022). "Therefore, it is plausible to surmise that the reduction in obesity-induced ATM and systematic inflammation in the HF + HVD group might be associated with the inhibitory effect of vitamin D on NLRP3-related IL-1β levels." (PMID 36142842, 2022). "Conversely, as obesity progresses, most ATMs are converted from an anti-inflammatory (M2-like) phenotype into a pro-inflammatory (M1-like) phenotype, secreting pro-inflammatory cytokines (such as TNF-α, IL-1β) and causing localized and systemic chronic low-grade inflammation, especially in WAT." (PMID 35563728, 2022). "However, OT intervention exerted a preventive effect on obesity possibly by regulating β-oxidation of fatty acid (Ppara and Pgc1a), cholesterol removal (Lxra), lipolysis (Srebf1 and Hsl), and low-grade inflammation (Il-6 and Il-1b)." (PMID 35967777, 2022). "Since obesity correlates with low grade inflammation and obese adipose tissue can be heavily infiltrated by immune cells, the mRNA levels of specific immune cell markers (Itgam and Il1b) and of tissue chemokines (Il6 and Ccl2) were quantified in pWAT, eWAT and iWAT." (PMID 36138030, 2022). "Steatohepatitis promotes the progression of psoriasis in patients with NASH, and obesity exaggerates the severity of psoriasiform dermatitis caused by the Toll-like receptor 7 (TLR-7) agonist imiquimod (IMQ) by promoting IL-17A and IL-22 secretion and IL-1β overexpression in HFD-fed mice." (PMID 34944732, 2021). "However, in the present study, it failed to measure because most of the levels were beyond the detecting range of the kit, which raises an important point that leptin may be a more sensitive indicator than IL-1β in HFD-induced obesity-related OA rats." (PMID 34457118, 2021).
Obesity (continued). "Published literature shows that lotus leaf reduces the levels of inflammatory cytokines IL-1β, TNF-α, IFN-γ, and IL-6, increases the levels of anti-inflammatory cytokines IL-4 and IL-10, and inhibits inflammation caused by high-fat diets accompanied by obesity." (PMID 34992717, 2021). "Regarding IL-1β, which in our results was also found to be reduced 6 months after the surgery, in a study in which follow-up was carried out only at 12 months after bariatric surgery, 32 subjects with obesity that underwent either RYGB or SG presented lower levels of IL-1β15." (PMID 34108550, 2021). "Therefore, we hypothesized that yeast microcapsules as IL-1β shRNA delivery vehicle has potential application value in the treatment of obesity via the oral route." (PMID 34683827, 2021). "Permeability of the BBB has previously reported to be increased in a mouse model of obesity-induced by high-fat diet, in which cognitive deficits were aggravated by excessive exposure of the brain to inflammatory cytokines, including LPS, IL-1β, IL-6, and TNFα." (PMID 32127019, 2020). "To identify signals in fat tissue that might induce YAP/TAZ activation during obesity, we analyzed whether palmitic acid or several cytokines, including TNFα, interleukin (IL)-1β, CCL2, and IL-6 are able to induce YAP/TAZ target gene expression in 3T3-L1 adipocytes." (PMID 33116140, 2020). "This is an intriguing point, as IL-1β is emerging as a critical player in several obesity-related comorbidities (i.e., insulin resistance, meta-inflammatory condition, cardiovascular diseases), and thus the enteric glia could participate in the maintenance of such disorders." (PMID 32443525, 2020). "Obesity is well-known to increase various pro-inflammatory adipokine concentrations in serum and plasma as well as adipose tissue, whereas mRNA expression levels showed that adipocytes co-cultivated with breast cancer cells also had significantly higher IL-6, IL-1β, and TNF-α levels." (PMID 32257945, 2020). "The water extract of A. camphorata ameliorates high-fat diet-induced obesity in mice by maintaining intestinal integrity, regulating intestinal microbiota to reduce fat accumulation and serum TG level and reversing inflammatory factors such as IL-1β, IL-6 and TNF-α." (PMID 32932919, 2020). "An unbalanced ω-6/ω-3 ratio is highly proinflammatory in terms of arachidonic acid metabolism and IL-1β production contributes to the prevalence of atherosclerosis and obesity, which may be a potential factor for increased risk of stones in atherosclerosis patients and obese people." (PMID 32973524, 2020). "Hence, obesity-associated increases in CCL2 and CCL5 levels, together with an increase in estrogen and pro-inflammatory mediators such as leptin, IL-6, IL-1β, and TNF-α could facilitate MDSC accumulation." (PMID 31475003, 2019). "In addition, it may be involved in OA progression in serum and synovial fluid by the regulation of pro-inflammatory markers such as IL-1β, IL-6, IP-10, and leptin in the obesity condition." (PMID 29843440, 2018). "Furthermore, serum and synovial fluid may be involved in OA progression through the regulation of pro-inflammatory markers such as IL-1β, IL-6, IP-10, and leptin in obesity conditions." (PMID 29843440, 2018). "Hence, lunasin decreased IL-1β secretion after leptin activation alone, indicating that this suppression might reduce obesity-induced inflammation and metabolic complications." (PMID 28182687, 2017). "IL-1β acting in a paracrine manner in adipocytes stimulated the production of IL-8, a potent chemoattractant involved in the adhesion of monocytes to endothelium and in the migration of vascular smooth cells, proposed therefore as a mediator between obesity and atherosclerosis." (PMID 26516848, 2015).
Obesity (continued). "In obese individuals investigated in our study, IL-1β protein levels in VAT were higher compared to normal-weight patients, especially in those diagnosed with metabolic syndrome, further supporting the role of this cytokine in the development of obesity-associated complications." (PMID 26516848, 2015). "The links between obesity, insulin resistance, and immune function have provided the basis for the emerging field of immunometabolism which implicates immune cell infiltration and increased expression of inflammatory mediators such as TNFα and IL‐1β in the pathophysiology of metabolic disease." (PMID 25096554, 2014). "Obesity and elevated IL-1β levels in OC patients may contribute to OC mortality." (PMID 25403235, 2014). "The association between IL-1B C-31T polymorphism and obesity has not been investigated in Japanese." (PMID 19398847, 2009). "Consistent with previous studies, we found that obesity promoted a shift toward M1 macrophage dominance, characterized by increased circulating pro-inflammatory cytokines including TNF-α, IL-6, and IL-1β." (PMID 41556049, 2026). "Principal component analysis (PCA) revealed two dominant components separating metabolic (irisin, HOMA-IR, insulin, BMI) and inflammatory (IL-1β, CCL2) profiles, supporting the distinction between metabolic and inflammatory pathways in obesity." (PMID 42196825, 2026). "Interestingly, a meta-analysis of 50 lifestyle programs found that combining physical activity/exercise with dietary/nutritional changes is likely to lower CRP, IL-6, and IL-1β concentrations, and may also reduce IL-8 in healthy children and adolescents who have overweight or obesity." (PMID 41515266, 2026). "Obesity further exacerbates this effect by creating a chronic inflammatory environment (with elevated TNF-α and IL-1β from adipose tissue) that synergizes with microbiota-driven inflammation." (PMID 41374093, 2025). "It is an important phenotype of obesity characterized by increased levels of proinflammatory cytokines, such as TNF‐α, IFN‐γ, IL‐1β, and IL‐6." (PMID 39968210, 2025). "In patients with obesity, insulin resistance can be triggered by WAT inflammation, as WAT inflammation leads to the release of pro-inflammatory cytokines, such as TNFα, IL-1β, IL-6, that inhibit insulin signaling and impaired glucose uptake." (PMID 40456448, 2025). "6-Shogaol inhibited IL-1β secretion by blocking NLRP3 inflammasome activation and reduced TNF-α levels, demonstrating a relevant anti-inflammatory effect in the context of obesity." (PMID 40733199, 2025). "In experimental models of dietary obesity, chelation with DFP and DFO has been shown to reduce IL-1β expression, normalize insulin signaling, and reduce macrophage infiltration into adipose tissue." (PMID 40943225, 2025). "Inflammatory markers, including CD16, CD11c, CCR2, CCR5, TNF-α, IL-1β, IL-2, IL-12, CCL8, CCL19, and CXCL9, were positively correlated with IL-23 in the AT-compartment in the obesity context." (PMID 41158638, 2025). "As observed in other tissues, obesity also induces inflammation in the testes, mainly through the overexpression of TNF-α, inducible nitric oxide synthase (iNOS), and IL-1β, accompanied by the underexpression of IL-10." (PMID 40002337, 2025). "In individuals with obesity-related insulin resistance, hypertrophied adipocytes exhibit increased secretion of pro-inflammatory cytokines, such as TNF-α, IL-6, and IL-1β, all of which impair insulin signaling by activating NF-κB and JNK pathways." (PMID 40563357, 2025). "The significantly increased levels of IL‐1β, IL‐6, and TNF‐α, in HFD‐fed mice are consistent with the well‐established link between obesity and chronic low‐grade inflammation, often referred to as “metaflammation”." (PMID 41245183, 2025). "The upregulated levels of IL1B in the VAT from patients with OB and CC found in our study, are in accordance with previous results showing that obesity increases the release of IL-1β in AT." (PMID 39305371, 2025).
Obesity (continued). "TNF-α levels are inversely correlated with insulin sensitivity, while IL-6 and IL-1β inhibit insulin receptor substrate 1 (IRS-1); moreover, elevated levels of leptin in women with pregestational obesity contribute to insulin resistance." (PMID 41374008, 2025). "In obesity, chronic stimuli like free fatty acids and oxidized lipoproteins maintain NLRP3 activation, increasing IL-1β and IL-18 levels." (PMID 40004007, 2025). "In the current study, HFD-induced obesity in rats was accompanied by the upregulation of inflammatory factors, whereas L. reuteri HM108 substantially reduced serum LPS and IL-1β levels." (PMID 40635899, 2025). "In stark contrast to AIM2, ablation of key components of the inflammasome, such as NLRP1, NLRP3, ASC, caspase‐1, and IL‐1β, protects mice from HFD‐induced obesity and insulin resistance." (PMID 39158380, 2025). "By secreting inflammatory molecules such as IL-6, IL-1β, and TNF-α, macrophages drive inflammation, exacerbating obesity, insulin resistance, and type 2 diabetes." (PMID 40453651, 2025). "Chronic low-grade inflammation is an important feature of obesity, involving the accumulation of macrophages in adipose tissue and the recruitment of additional inflammatory factors such as TNF-α and IL-1β." (PMID 40308638, 2025). "As obesity is a state of IR, adipose tissue can secrete tumor necrosis factor (TNF‐α), interleukin‐6 (IL‐6), interleukin‐1β (IL‐1β) and other substances." (PMID 41245183, 2025). "These include cytokines crucial in the pathophysiology of obesity, such as tumor necrosis factor alpha (TNF-α), interleukin-6 (IL-6), and interleukin-1β (IL-1β), thus perpetuating the chronic low-grade inflammatory state." (PMID 41153608, 2025). "Further, adolescents with obesity have shown higher orofacial pain severity at 24 h after OTM, as well as higher IL-1β levels before and during OTM, compared with adolescents without obesity." (PMID 40724937, 2025). "The levels of caspase‐1 activity in adipose tissue or circulating IL‐1β are similar in obese WT and Aim2−/− mice, suggesting that AIM2 prevents obesity independently of its inflammasome activity." (PMID 39158380, 2025). "In obesity, pro-inflammatory adipocytes-derived cytokines (IL-6, TNF-α, and IL-1β) and C-reactive protein (CRP) are often elevated." (PMID 41375608, 2025). "The adipose tissue of individuals with obesity releases pro-inflammatory adipokines such as TNF and IL-1β." (PMID 41153608, 2025). "Obesity can skew the adipose tissue to secrete adipokines, including MCP-1, TNF-α, IL-1β, and IL-6, which perpetuate a low-grade inflammation or meta-inflammation." (PMID 41472730, 2025). "Emerging evidence suggests that ceramide activation plays a crucial role in triggering caspase-1 activation and IL-1β production via the NLRP3 inflammasome pathway, contributing to pathological conditions like obesity, podocyte damage, and acute lung injury." (PMID 40002829, 2025). "Pro-inflammatory cytokines (e.g., TNF-α, IL-1β, IL-6, MCP-1) contribute to metabolic disorders such as obesity and diabetes." (PMID 40573106, 2025). "Moreover, Obesity may increase inflammatory factors, IL-6, IL-8, and IL-1β, thereby increasing IR." (PMID 40162320, 2025). "The authors applaud the results of a clinical study in which clinical periodontal inflammatory parameters and whole salivary IL-6 and IL-1β were significantly higher among patients with class II and III obesity than patients with class I obesity." (PMID 41396032, 2025). "In obesity, adipocytes produce and release a variety of inflammatory factors, such as TNF- α and IL-1β." (PMID 40428495, 2025). "Secondly, IL-1β, IL-6, TNF-α, and IL-18 are overexpressed in obesity, contributing to the development of nephropathy by promoting inflammation." (PMID 40703753, 2025). "IL-1β was measured in both serum and liver tissuesdue to its critical involvement in nonalcoholic fatty liver disease(NAFLD), a condition prevalent in obesity and type 2 diabetes." (PMID 38973907, 2024).
Obesity (continued). "Obesity is considered a chronic inflammatory state, with adipocytes secreting inflammatory cytokines such as IFN-γ, TNFα, and IL-1β." (PMID 38898891, 2024). "For instance, SM (60 mg/kg) was illustrated to reduce inflammation (TNF-α, IL-1β and IL-6) and to mitigate liver damage and insulin resistance in a model of HFD-induced obesity mice." (PMID 38247522, 2024). "Our current study shows that HFD-induced obesity exacerbates allergic asthma via the action of different cytokines (IL-17, TGF-β, TNFα, and IL-1β) known to regulate lung damages and neutrophilic inflammation." (PMID 38892358, 2024). "In pregnant women, both obesity and diabetes increase pro-inflammatory cytokines and adipokines, such as TNF-α, IL-6, IL-1β, leptin, and resistin, which are involved in the inflammatory response." (PMID 39584800, 2024). "Consequently, the significant reductions in PBMC gene expressions of IL-6, IL-1β, and leptin, marked by their comparatively large effect sizes, collectively point toward a potential state of controlled inflammation in the realm of obesity subsequent to NS oil supplementation." (PMID 38178093, 2024). "Our results highlight the overexpression of TNFα and IL-1β in the obesity group, while the CRP was significantly higher on the obesity group compared to the controls; this correlates with the elevated BMI and low plasma iron distribution in the obese patients." (PMID 39057082, 2024). "Accumulated data confirmed the ameliorative effects of SM in adipose tissue inflammation (decreased expression of IL-1β and TNF-α and increased expression of IL-10 and adiponectin) in an HFD-induced obesity model in mice." (PMID 38247522, 2024). "In C57BL/6J (B6) obese mice induced by genetic obesity (db/db) and high-fat and high-sugar diet, nicotine inhibited the increase of F4/80 in obesity-induced inflammation and the levels of proinflammatory cytokines such as TNF-α, IL-6, IL-1β and iNOS in serum." (PMID 38681197, 2024). "The initiation of inflammatory pathways and up-regulated cytokines like IL-1β, IL-6 and TNF-α also contribute to obesity and IR development." (PMID 38163110, 2024). "A previous study reported that increasing levels of TNFα and IL1β impairs the phosphorylation of IRS1/2 via severe mechanisms (MAPK, JNK and IKK) in obesity, resulting in insulin resistance in liver and adipose tissues." (PMID 38338579, 2024). "Here, administration of reticuline decreased the production of IL‐17A, MIP‐2, IL‐1β, IL‐5, and RANTES in lung tissues of mice with obesity‐related asthma induced by HDM or OVA." (PMID 38286741, 2024). "In a fructose-induced obesity model, SPX injection was found to significantly reduce the levels of pro-inflammatory cytokines (TNF-α, IL-1β, and IL-6) in the epididymal adipose tissue of mice." (PMID 38234666, 2024). "The cytokine production capacity of children with obesity was higher for TNF, IL-1β, IL-6, IL-10, IL-1Ra, IL-12p70, MCP-1, RANTES, and MIP1α, but not IL-8, indicating an overall hyperresponsive state compared to controls." (PMID 38741712, 2024). "Tumor tissues from HFD-IF mice diminished C5, IL-1β, CCL3, and CXCL2 protein levels compared to those from HFD mice, indicating that IF attenuates obesity-induced inflammatory conditions in the tumor microenvironment." (PMID 38999849, 2024). "What is well established in humans is the increased presence of proinflammatory markers of inflammation such as IL-1β, TNF-α, and IL-6 within AT of individuals with obesity." (PMID 38206766, 2024). "What is the functional outcome of targeting IL-6 trans-signaling in the presence of other cytokines (IL-1β, TNF-α, and IL-18) in obesity?" (PMID 39125976, 2024). "We found that the levels of IL‐1β and CXCL16 were upregulated in the mammary glands of mice at the pre‐obesity stage." (PMID 38145352, 2024).